IDH1 (isocitrate dehydrogenase (NADP(+)) 1)
Diseases named in the same sentence as IDH1 in open-access papers (continued):
Sharing a sentence is not in itself a finding about the gene and the disease.
glioma (continued). "IDH1-R132H, which is associated with better prognosis in glioma, catalyzes 2-hydroxyglutarate production, prompting epigenetic reprogramming of the glioma transcriptome." (PMID 34422657, 2021). "IDH1 and IDH2 mutations have been co-targeted though molecules such as AG-881, which is currently being evaluated in the phase 3 INDIGO trial (NCT04164901) in patients with residual or recurrent Grade 2 glioma with an IDH1 or IDH2 mutation." (PMID 34222022, 2021). "Analyses were done in clinical specimen of different glioma subtypes, in glioma patient-derived cell lines carrying the endogenous IDH1 mutation and corresponding orthotopic xenografts in mice." (PMID 34250481, 2021). "Gain-of-function mutations in the IDH1 gene occurs in various human cancers, including colorectal cancer and glioma, which disrupt NADPH homeostasis by consuming NADPH for 2-hydroxyglutarate (2-HG) synthesis." (PMID 33808242, 2021). "A comparison of the transcriptomic landscape of glioma with wild-type and mutated IDH1 revealed that the cell cycle- and EMT-related terms were significantly enriched." (PMID 34205437, 2021). "Previously it was shown that glioma tumor cells with IDH1 mutation highly produce 2-hydroxyglutarate (2HG) and considered as a biomarker for IDH1 mutation." (PMID 34150663, 2021). "Despite the direct impact of IDH1 mutation on lipid biosynthesis, little is known about how this altered lipid metabolism affects cellular function specifically in IDH1mut gliomas." (PMID 33504762, 2021). "For example, mutations in the isocitrate dehydrogenase 1 (IDH1) gene have been identified as driver mutations in many gliomas." (PMID 32542524, 2021). "In this regard, the role of early events during gliomagenesis, such as IDH1 mutations, in driving multicentric gliomas remains elusive." (PMID 34587990, 2021). "Gliomas with IDH1 mutations have relatively better outcomes and superior responses to therapy than those with the wildtype IDH1 gene." (PMID 34804371, 2021). "IDH1 mutations (IDHmut) are present in more than 80% of low-grade gliomas (grades II-III) and in secondary GBMs, but are rare in primary GBMs." (PMID 34178638, 2021). "IDH1 point mutations, most commonly R132H, drive > 80% of lower grade gliomas and secondary glioblastomas by catalyzing the neomorphic production of the oncometabolite D-2-hydroxyglutarate (D2HG) from αKG." (PMID 34065652, 2021). "The understanding of altered lipid metabolism by isocitrate dehydrogenase 1 (IDH1) mutations in gliomas at a compartment-specific level is limited." (PMID 33504762, 2021). "This review reports predominantly on glioma models because it reflects their extensive use in the literature on IDH1/2 mutations to date." (PMID 35028610, 2021). "IDH1 mutations occur early in glioma-genesis and occur in a progenitor cell that can give rise to both cell types." (PMID 34070746, 2021). "An intriguing cross-talk occurs between the three enzymes of TCA cycle producing oncometabolites in glioma with mutated IDH1." (PMID 34065551, 2021). "The relatively recent discovery of the IDH1/2 mutations was a crucial observation that has impacted the way the World Health Organization now classifies gliomas." (PMID 33668509, 2021). "Both subventricular zone (SVZ) contact and isocitrate dehydrogenase 1 (IDH1) mutation have been reported to be related to the outcome of glioma, respectively." (PMID 34490090, 2021). "In this study, we tested the possible utility of fractal dimension from MET uptake in patients with newly diagnosed gliomas for differentiating glioma, especially in relation to IDH1 mutation status." (PMID 34743250, 2021). "Other authors demonstrated that the mutation of IDH1 inhibits the growth of glioma cells, possibly mediating prolonged survival in the glioma." (PMID 34573039, 2021). "The higher mutation frequencies were mainly related to BRAF V600E mutations in thyroid cancer (61.8%) and melanoma (43.6%) and IDH1 R132H mutations in low-grade glioma (70.1%)." (PMID 33556087, 2021).
glioma (continued). "The phase 1 clinical trial in patients with gene IDH1-mutated gliomas (NCT03030066) showed good tolerance with favorable brain distribution; current work has determined the recommended dose for the phase 2 trial." (PMID 34571995, 2021). "Genome-wide exon-sequencing studies of gliomas have revealed IDH1 R132H activating point mutations in as many as 80–90% of low-grade gliomas (LGGs)." (PMID 34277624, 2021). "This study aims to specifically identify co-occurring mutations and gene expression patterns in IDH1-mutant glioma using a genome-wide approach, with the aim to improve glioma genetic profiling and understand how an IDH1 mutation influences this." (PMID 34503108, 2021). "Either IDH1 or IDH2 mutations are a defining classification for adult gliomas, with vast majority of gliomas as IDH1 mutations." (PMID 33599882, 2021). "Our previous studies in cells have identified the MRS-detectable metabolic alterations characteristic of glioma harboring the IDH1 mutation when compared to wild type IDH1." (PMID 33668509, 2021). "This was true when we assessed all glioma samples and when we restricted the analysis to only include IDH1/2 mutated samples." (PMID 33778493, 2021). "We also found that TP73-AS1 expression levels were significantly correlated with the WHO grade of gliomas (p <0.0001), IDH1 mutation (p=0.0035), and 1p/19q co-deletion state (p=0.0119)." (PMID 33589576, 2021). "Since the initial discovery of recurrent isocitrate dehydrogenase 1 (IDH1) mutations at Arg132 in glioma, IDH1 hotspot mutations have been identified in cholangiocarcinoma, chondrosarcoma, leukemia, and various other types of cancer of sporadic incidence." (PMID 34440884, 2021). "The frequency of IDH1 mutation in lower-grade glioma, however, was conspicuously high (77%) in TCGA_PanCancer, with cholangiocarcinoma and acute myeloid leukemia much lower at 14% and <10%, respectively." (PMID 34440884, 2021). "Accumulating studies have shown that IDH1 mutations are related to the occurrence and development of glioma, and IDH1 mutations are more common in LGG(WHO II, WHO III) than in GBM(WHO IV)." (PMID 33996568, 2021). "The present study aimed to investigate the association between oral microbiota and grade of glioma and examine the relationship between malignancy-related oral microbial features and the isocitrate dehydrogenase 1 (IDH1) mutation in glioma." (PMID 34733261, 2021). "For example, the identification of IDH1/2 mutations in adult gliomas was a landmark discovery in adult brain tumor management." (PMID 33931704, 2021). "Somatic mutations in IDH1 genes have recently been identified in a large proportion of glial tumors of the CNS." (PMID 34070746, 2021). "Since 2008, sequencing of gliomas has identified IDH1 mutations and the nature of these mutations vary, according to cancer types." (PMID 33419230, 2021). "Mutations in the isocitrate dehydrogenase-1 and -2 (IDH1/2) genes were first identified in glioma and acute myeloid leukemia (AML), and subsequently found in multiple other tumor types." (PMID 34027408, 2021). "Within low-grade gliomas and secondary glioblastoma, 2HG is often produced due to mutations in the catalytic domains of isocitrate dehydrogenase isoform 1 (IDH1) and isocitrate dehydrogenase isoform 2 (IDH2)." (PMID 34222022, 2021). "IDH1 harbored somatic mutations overall in 34% (314/923) of gliomas, whilst its presence significantly predicts an improved overall survival (OS) and better progression-free survival (PFS)." (PMID 35996504, 2021).
glioma (continued). "Analysis showed that UBE2S expression was positively associated with PTEN-mutation and EGFR amplification and negatively associated to IDH1-mutation and co-deletion of 1p19q in whole grade glioma." (PMID 34123793, 2021). "Flux of pyruvate through PC was similarly increased in glioma cells containing an isocitrate dehydrogenase 1 (IDH1) mutation in which glutamine-derived αKG is preferentially converted to 2-hydroxyglutarate, leading to depletion of TCA cycle intermediates." (PMID 33931119, 2021). "Studies have found that the degree of GAMs invasion is correlated with tumor grade, and differences in GAMs were found in the microenvironment of gliomas with different isocitrate dehydrogenase 1/2 (IDH1/2) somatic mutation types." (PMID 34659216, 2021). "There are many well-studied pathogenic genes and regulators of gliomas, including IDH1/2, 1p/19q codeletion, integrin β1 (ITGB1) and v-raf murine sarcoma viral oncogene homolog B1 (BRAF) V600E mutation." (PMID 34722629, 2021). "Evidence for altered PC anaplerosis was further documented in more than 70% of low-grade gliomas harboring point mutations in the isocitrate dehydrogenase 1 (IDH1) gene that typically involve the Arg132 residue." (PMID 33808495, 2021). "Certainly, animal and cell experiments are further needed to determine the causality of IDH1 mutation on the oral microbiome under glioma status." (PMID 34733261, 2021). "The most striking negative associations between mutations and age in low-grade glioma and glioblastoma were found in IDH1 (OR = 0.9509 and 0.8962, 95% CI = 0.9328–0.9686 and 0.8598–0.9291, adj." (PMID 33879792, 2021). "Despite the role of IDH1 enzyme in lipogenesis and its frequent mutation in gliomas, very few studies have addressed the impact of IDH1 mutation to lipid synthesis." (PMID 33504762, 2021). "Our findings are consistent with reports from previous studies that IDH1 mutation are correlated with more favorable OS implying that IDH1 mutations play a critical role in glioma patients." (PMID 34604305, 2021). "IDH1 mutations, primarily R132H, drive > 80% of low-grade gliomas and secondary glioblastomas and facilitate the NADPH-dependent reduction of αKG to the oncometabolite D-2-hydroxyglutarate (D2HG)." (PMID 34065652, 2021). "The genera Bergeyella and Capnocytophaga were significantly more positively correlated with the IDH1 mutation in gliomas when compared with the IDH1-wild-type group." (PMID 34733261, 2021). "The latest WHO classification of CNS tumors termed gliomas of WHO grades I–III together as “lower-grade gliomas” with a great majority of IDH1 mutations and a wide range of overall survival within this group." (PMID 34671241, 2021). "On the contrary, the risk of VTE has been reported to be extremely low in patients with IDH1 mutated gliomas." (PMID 33828976, 2021). "Mutations in isocitrate dehydrogenase 1 or 2 (IDH1/2) define glioma subtypes and are considered primary events in gliomagenesis, impacting tumor epigenetics and metabolism." (PMID 34250481, 2021). "To confirm these results, we used a cell line (named LGG275) that was derived from a diffuse low-grade glioma patient with IDH1 and ATRX mutations." (PMID 33925547, 2021). "We found that the 2HG detection by MRS was useful in the selection of glioma cases with rare IDH1 and IDH2 mutations." (PMID 34829476, 2021). "Mutations in the IDH1 gene are an important molecular markers identified in recent years and are closely associated with the development of gliomas." (PMID 34603319, 2021). "Particularly, IDH1 R132H was the most frequent mutation identified, comprising 84% (236/281) of IDH1/2-mutated gliomas." (PMID 33778493, 2021). "One excellent example of this is gliomas, which show a strong preference for the R132H mutation of isocitrate dehydrogenase (IDH1;)." (PMID 34944895, 2021).
glioma (continued). "Mutations in isocitrate dehydrogenase 1 and 2 (termed IDH1/2mut) are present in approximately 25–30% of all diffusely infiltrative gliomas in adults, and are now part of the diagnostic criteria for oligodendrogliomas." (PMID 34424450, 2021). "Gliomas with IDH1 mutation were found to have significantly reduced hypoxia-inducible factor 1α (HIF-1α) and decreased neovascularization." (PMID 34671241, 2021). "Mutations in isocitrate dehydrogenase 1 or 2 (IDH1/2) are frequently detected in patients with glioma." (PMID 34359742, 2021). "Several concurrent studies confirmed this finding and further revealed that the mutations in IDH1/2 are more prevalent in gliomas with lower pathologic grades." (PMID 34571995, 2021). "Somatic heterozygous hotspot mutations in isocitrate dehydrogenase 1 and 2 (IDH1/2) are observed in about 80% of glioma." (PMID 33681204, 2021). "Given the accuracy of this caller across all samples, we investigated the 1p19q codeletion status specifically across IDH1/2-mutated glioma samples and compared our calls to FISH results." (PMID 33778493, 2021). "Studies in glioma and leukemia have helped promote the theory that IDH1 mutations are an oncogenic event that drives tumorigenesis in general." (PMID 34440884, 2021). "A genome-wide profiling of glioma patients in the Catalogue of Somatic Mutations in Cancer (COSMIC) database was performed to classify the genetic differences in IDH1-mutant versus IDH1-wildtype patients." (PMID 34503108, 2021). "Many studies have been performed in recent years and suggest that mutated IDH1 participates in the pathogenesis of glioma." (PMID 33708242, 2021). "Previous data showed that intratumoral thymidine from necrotic cells inhibited GCLC activity and that GCLC expression was upregulated in IDH1-mutated compared to IDH1 wild-type glioma." (PMID 34568059, 2021). "Amongst the molecular genetic alterations used to redefine glioma entities, the most common are mutations in the isocitrate dehydrogenase 1 and 2 (IDH1, IDH2) genes and the 1 p/19q co-deletion status." (PMID 33916593, 2021). "Glioma patients with IDH1 hotspot mutations are known to have better survival than those without such mutations, but astrocytoma patients with non-canonical IDH1R132X have even longer survival than those with IDH1R132H." (PMID 34440884, 2021). "ATRX loss often co-occurs with glioma-associated mutations in other genes, such as isocitrate dehydrogenase-1 and -2 (IDH1/2)." (PMID 34118569, 2021). "Another phase 2 trial of DS-1001b in patients with chemo- and radiotherapy-naive IDH1 mutated WHO Grade II Glioma (NCT04458272) is ongoing." (PMID 34571995, 2021). "IDH1 mutations in some gliomas, and IDH1 and IDH2 mutations in some acute myeloblastic leukemias, convert αKG to R-2-hydroxyglutarate (2HG)." (PMID 34631530, 2021). "CHI3L1 and NTRK2 were identified as factors that can be associated with IDH1 status and 1p/19q codeletion to distinguish between prognostic groups of glioma from the TCGA cohort." (PMID 34458259, 2021). "Perhaps counterintuitively, the presence of this mutation is associated with better prognoses compared with glioma patients with a wildtype IDH1." (PMID 34944895, 2021). "In glioma, patients with an IDH1 mutation have a relatively prolonged survival, whereas prognosis of other IDH1/2-mutated tumors remains poor." (PMID 34069550, 2021). "Accumulating evidence indicates that SVZ and IDH1 mutation are the leading determinants for prognostic prediction of glioma." (PMID 34490090, 2021). "The stimulation of HIF-1α and the process of angiogenesis appears to be activated only when hypoxia occurs in IDH1-mutated gliomas." (PMID 34070746, 2021). "Mutations affecting IDH2 and additional IDH1 variants have also been reported in gliomas, but at a lower frequency, with the majority conferring similar changes in IDH activity." (PMID 34277624, 2021).
glioma (continued). "It is worth noting that IDH1R132H inhibitor BAY1436032 collocated with PD-1 inhibitor would result in an increase of overall survival in C57BL/6 J mice bearing IDH1-mutated glioma." (PMID 34425876, 2021). "IDH1/2 mutations in some gliomas are associated with longer survival and better responses to chemotherapy." (PMID 34571910, 2021). "IDH mutations in gliomas occur more frequently at residue p.R132 of IDH1 and residue p.R172 of IDH2." (PMID 34165590, 2021). "The activation of the AMPK signaling pathway contributes to the anti-inflammatory microenvironment of IDH1-mutated gliomas and thus causes better prognoses in patients with an IDH1-mutated glioma." (PMID 34733261, 2021). "Isocitrate dehydrogenase 1 (IDH1) mutations are common in low-grade gliomas (>80%) and secondary glioblastomas (73%) but are rare in primary glioblastomas (3.7%)." (PMID 34067762, 2021). "It was reported that the expression levels of xCT were found to be associated with seizures and identified as an independent biomarker for glioma-associated seizures, also in a cohort of IDH1-wildtype glioblastoma patients." (PMID 34067762, 2021). "The latest World Health Organization classification of gliomas incorporated the mutation status of IDH-1 based on histology." (PMID 35111665, 2021). "Understanding the unique metabolic profile reprogrammed by IDH1 mutation has the potential to identify new molecular targets for glioma therapy." (PMID 33504762, 2021). "The phase 1/2 clinical trial of AG-221 (NCT02273739) was completed in advanced solid tumors with IDH1 mutation, including glioma." (PMID 34571995, 2021). "In conclusion, our work revealed oral microbiota features and gene functions that were associated with glioma malignancy and the IDH1 mutation in glioma." (PMID 34733261, 2021). "Overall, approximately 80% of lower-grade gliomas and secondary glioblastomas harbor an IDH1 or IDH2 mutation, thus supporting the inclusion of this class of mutations in mouse models of these glioma subtypes." (PMID 33806933, 2021). "Recently, mutations in isocitrate dehydrogenase 1 and 2 (IDH1/2) have been identified in the majority of lower-grade gliomas and a relatively small subset of GBMs." (PMID 33806933, 2021). "Additional studies have revealed frequent IDH1/2 mutations in a variety of human cancers, including 70%-80% of low-grade gliomas, 50%-70% of chondrosarcomas, 10–20% of intrahepatic cholangiocarcinoma and approximately 20% of acute myeloid leukemia (AML)." (PMID 34516556, 2021). "IDH1R132H, the IDH1/2 mutation with relatively low D-2HG production capacity, is the most common mutation in gliomas; other mutations such as IDH1R132C have tenfold lower KM and have higher enzymatic efficiency." (PMID 33740099, 2021). "This study model proposed that IDH1 mutation affects glioma proliferation by altering clock gene expression through the TGF-ß/Smad signaling pathway." (PMID 34361055, 2021). "We performed extensive molecular analysis of tumor samples, classified according to their isocitrate dehydrogenase (IDH1) gene mutation status, and of glioma stem cells." (PMID 33720519, 2021). "A meta-analysis of 55 observational studies revealed glioma patients harboring IDH1 mutations have improved OS and PFS, especially for patients with WHO grade III and grades II–III." (PMID 34490090, 2021). "IDH1-mutated gliomas also exhibit an increase in levels of vascular endothelial growth factor when compared with gliomas without IDH1 mutations of similar type and grade." (PMID 34707087, 2021).